PMS1 (PMS1 homolog 1, mismatch repair system component)
Diseases named in the same sentence as PMS1 in open-access papers (continued):
Sharing a sentence is not in itself a finding about the gene and the disease.
cancer (47 papers, 2005 to 2025). A tumor composed of atypical neoplastic, often pleomorphic cells that invade other tissues. "The powers to detect the observed effect sizes in tobacco-smoking cases of Mixed Ancestry group remained sufficient for MSH3 rs26279 (97.53%) and MLH3 rs28756991 (85.05%), whereas borderline association of PMS1 rs5742938 with cancer was underpowered at 64.06%." (PMID 22623965, 2012). "Secondly, we observed that a homozygous genotype for the G-allele in the PMS1 rs5742938 polymorphism was associated with cancer in Mixed-ancestry South Africans." (PMID 22623965, 2012). "The other important genes in this pathway like Abl1, Gml, Brca1, Zak, Xrcc5, Trex1, Pms1, Ccnu and Apex2 were also up regulated in the cancer cells." (PMID 22321936, 2012). "Strengths of this work were to demonstrate that the PMS1 gene is probably not a predisposition cancer gene." (PMID 39436407, 2024). "PMS1 is a mismatch repair gene that plays an important role in cancer and some genetic diseases." (PMID 35158649, 2022). "Upregulation of the PMS1 gene was also found in cancer patients." (PMID 35740268, 2022). "Although we thoroughly examined the genetic alterations in this patient, it remains to be answered whether PMS1 (p.D300fs) alone is sufficient to induce cancer." (PMID 32000458, 2020). "Mutations in the mismatch repair gene PMS1 and the actin cytoskeleton remodelling gene FNBP1 were subclonally fixed in hEMT cancers, potentially suggesting that acquiring such alterations later during tumour evolution may benefit the establishment of a hybrid phenotype." (PMID 36774358, 2023).
cancer (continued). "In addition, while mutations in MSH3 and MLH3 have been implicated in a variety of cancers and cancer predisposition syndromes, PMS1 mutations have not been definitively associated with any cancer predisposition to date either in mice or humans (see omim.org/entry/600258?search=pms1&highlight=pms1)." (PMID 32589669, 2020). "No PMS1 germline mutations have been reported in HCC, but a few have been reported in other cancers." (PMID 32000458, 2020). "Similarly to cancer tissues, in adjacent mucosal tissues, MLH3 correlated with PMS1 and PMS2 (R = 0.887 and R = 0.931, P < 0.000, respectively), but, additionally, MLH3 also correlated with MSH6 (R = 0.857, P < 0.0001)." (PMID 24484585, 2014). "Interestingly, screening for hereditary cancer genes revealed the presence of missense mutations in DNA mismatch repair genes — MSH6 (c.2039C > T) and PMS1 (c.321A > C), whose significance has not yet been established." (PMID 37658412, 2023).
tumor (29 papers, 2005 to 2025). "Bi-allelic loss of PMS1 was confirmed by immunohistochemistry in the infiltrating tumor area of the sample, whereas normal tissue retained PMS1 expression." (PMID 32295625, 2020). "Furthermore, PMS1 mutations can promote tumor development and progression by affecting cell cycle regulation, apoptosis, and other mechanisms." (PMID 39865406, 2025). "PMS1 is one of the MMR genes that play important roles in tumor occurrence, progression and prognosis." (PMID 32000458, 2020). "The spectrum of MPA tumor mutations was distinct from that observed in Mlh1−/−;Apc1638N mice, implicating the first potential role for MLH1/PMS1 in tumor suppression." (PMID 18551179, 2008). "Investigating MMR gene mutations and methylation status in MSI tumor samples, we only observed few cases of MSH6 (MutSα), MSH3 (MutSβ), PMS2 (MutLα), PMS1 (MutLβ), and MLH3 (MutLγ) high-impact mutations often in combination with inactivation of other MMR genes." (PMID 29636374, 2018). "In addition, there is functional compensation between MMR proteins (PMS2/PMS1, MSH6/MSH3), which can maintain the tumor MSS status in the absence of the four most frequently detected MMR proteins." (PMID 36591511, 2022).
adenocarcinoma (1 paper, 2016). A common cancer characterized by the presence of malignant glandular cells. "Three of the markers: GPR56, LY6G6D/F and SLCO1B3 had significantly higher expression in proximal adenocarcinomas and were positively correlated with mismatch repair protein expression, i.e. PMS2 and MSH6 with all three, and PMS1 with LY6G6D/F." (PMID 26894861, 2016).
infection (1 paper, 2013). The state of being infected such as from the introduction of a foreign agent such as serum, vaccine, antigenic substance or organism.
PMS1 also shares sentences with these, for which no sentence is quoted: Hereditary non-polyposis colorectal cancer (4 papers); colon cancer (2); Cowden syndrome (2); Fanconi anemia (2); prostate carcinoma (2); adenoma (1); anemia (1); bacterial infection (1); chronic lymphocytic leukemia (1); CMMR-D syndrome (1); dermatitis (1); endometrial tumors (1); Fanconi anemia complementation group E (1); gastrointestinal tumors (1); genetic diseases (1); Gorlin syndrome (1); invasive carcinoma (1); Li-Fraumeni syndrome (1); liver cirrhosis (1); lung squamous cell carcinoma (1); malignant pleural mesothelioma (1); mesothelioma (1); mucositis (1); myositis (1); neurodegenerative disease (1); oral squamous cell carcinoma (1); osteosarcoma (1); pancreatic adenocarcinoma (1); pancreatic ductal adenocarcinoma (1); polymyositis (1).
A further 4 diseases each share a sentence with PMS1 in 1 paper.